EGFR (epidermal growth factor receptor)
Diseases named in the same sentence as EGFR in open-access papers (continued):
Sharing a sentence is not in itself a finding about the gene and the disease.
ovarian carcinoma (continued). "Based on these findings, we suggest that 6-shogaol + gefitinib co-treatment may overcome EGFR-mediated resistance and induce a programmed cell death pathway via the excessive ER stress response in ovarian cancer cells and gefitinib-resistant cancer cells." (PMID 36768961, 2023). "Thus, we tested the EGFR levels in ovarian cancer cells according to the results obtained from the bioinformatics analysis." (PMID 38203692, 2023). "Several drug types that suppress stroma-immune signatures, such as EGFR inhibitors, could be candidates for potential immunotherapeutic combinations in ovarian cancer." (PMID 37658364, 2023). "Overall, our clinical and in vitro data supported that MICALL2 may participate in the process of immune reaction and promote ovarian cancer cell invasion via the EGFR pathway." (PMID 38203692, 2023). "Interestingly, both patients with SD ≥ 4 months harbored EGFR aberrations, including an ovarian cancer patient with KRAS G12D and EGFR G724S mutations and a salivary gland cancer patient with EGFR amplification by IHC." (PMID 37314501, 2023). "EGFR overexpression has been reported in 30-98% of epithelial ovarian cancers." (PMID 37213272, 2023). "The type I cGMP-dependent protein kinase (PKG I) is recognized as a tumor suppressor, but its role in EGFR regulated epithelial ovarian cancer (EOC) progression remains unclear." (PMID 36653376, 2023). "Based on these findings, we hypothesize that the functions of MICALL2 in promoting ovarian cancer cell invasion might be mediated by the stabilization of EGFR expression and, consequently, the activation of EGFR downstream signal pathways." (PMID 38203692, 2023). "This suggests that GE11-guided drug targeting could be an alternative approach to treat EGFR overexpressing ovarian cancer." (PMID 37213272, 2023). "Besides, CD24 and EGFR have also been characterized in exosomes derived from ovarian cancer patients and proposed to be potential biomarkers for ovarian cancer." (PMID 36109501, 2022). "For example, CX3CL1 as a chemokine has been associated with better patient outcomes by recruiting NK and CD8+ T cells in gastric adenocarcinoma; paradoxically, CX3CL1 was also found to stimulate the proliferation of gastric and ovarian cancer cells by activating EGFR." (PMID 36397015, 2022). "EGFR and phosphorylated EGFR could be widely detected in the ovarian cancer samples, and Gefitinib monotherapy could decrease their levels." (PMID 35372049, 2022). "The activation of EGFR signaling by fentanyl may provide a new guide in clinical use of fentanyl in ovarian cancer patients." (PMID 35999506, 2022). "Knockdown of EGFR abolished the stimulatory effects of fentanyl on ovarian cancer cells." (PMID 35999506, 2022). "EGFR has been shown to be overexpressed in ovarian cancer cells." (PMID 36248433, 2022). "Furthermore, MYC, EGFR, CCND1 exhibited close association with chemotherapeutic response to platinum and showed a high expression in ovarian cancer tissues and platinum-resistant ovarian cancer cells." (PMID 35739532, 2022). "As expected, EGFR depletion alone decreased ovarian cancer migration and proliferation." (PMID 35999506, 2022). "Hence, overexpression of the EGFR/ErbB receptor family members facilitates the progression of epithelial ovarian cancer." (PMID 35761259, 2022). "The preliminary results show that SK may play a role through the estrogen signal GPER and its downstream EGFR/PI3K/AKT pathway in the treatment of ovarian cancer and verified that GPER is the key pathway." (PMID 36248433, 2022). "Given the importance of EGFR in ovarian cancer and the fact that μ-opioid receptor agonists can activate EGFR, we hypothesized that fentanyl might display pro-ovarian cancer activity via simulating EGFR-mediated signaling." (PMID 35999506, 2022).
ovarian carcinoma (continued). "In ovarian cancers, activation of EGFR activation stimulates signalling cascades which could lead to increased expression of MMP‐9 and MT1‐MMP." (PMID 36448260, 2022). "Rab25-mediated EGFR recycling and elevated levels of nuclear EGFR correlate with poor prognosis in ovarian cancer, and our data which suggest that Rab25 may be connected with nuclear envelope-associated endosomes warrants further investigation." (PMID 35708998, 2022). "In ovarian cancer cells, berberine could reduce the expression of both EGFR and HER2 and suppress their targets, cyclin D1, matrix metalloproteinases and vascular endothelial growth factor (VEGF)." (PMID 35269825, 2022). "Studies have shown that miR-125a-5p could regulate tumor invasion, migration, and EMT by directly targeting the TAZ/EGFR pathway in both colorectal and ovarian cancers." (PMID 36101746, 2022). "Moreover, we also observed an increase in the expression level of mRNA and protein for EGFR in women with ovarian cancer." (PMID 35807169, 2022). "We speculate that the less activity of fentanyl l on normal cells compared with ovarian cancer cells might correlate with differential expression level of EGFR in normal and tumor cells." (PMID 35999506, 2022). "EGFR is the host gene of m7G_ID_149119 and its overexpression has been observed in 30%-98% of epithelial ovarian cancer in all histologic subtypes, and enhanced expression of EGFR is correlated with advanced-stage disease as well as poor response to chemotherapies." (PMID 33761868, 2021). "Interestingly, we have shown previously that EGFR inhibition upregulates BIM in ovarian cancer cells." (PMID 34160887, 2021). "Similarly, the combined PAFR and EGFR inhibition synergistically diminished ovarian cancer progression." (PMID 34571986, 2021). "However, EGFR inhibitor treatment similarly resulted in increased STAT3 phosphorylation in human ovarian cancer cells." (PMID 34369236, 2021). "We have shown previously that EGFR and Bcl-xL are direct targets of miR-491-5p and that their concomitant inhibition with specific pharmacological inhibitors is able to mimic miR-491-5p-induced cell death in ovarian cancer cells." (PMID 34439123, 2021). "Indeed, LPA-activated GPCRs have been shown to transactivate with EGFR to increase ovarian cancer cell invasiveness." (PMID 34065317, 2021). "However, the treatment of ovarian cancers with the anti-EGFR agent gefitinib alone generates a limited response." (PMID 34445495, 2021). "EGFR is also a promising potential target for the treatment of ovarian cancer." (PMID 34369236, 2021). "In addition, overexpression of ST3GAL1 can promote migration and peritoneal dissemination of ovarian cancer cells via the EGFR signaling." (PMID 33921986, 2021). "Additional studies are needed to verify the role of EGFR overexpression in artesunate resistance and to determine if EGFR inhibitors could sensitize ovarian cancer models, which would otherwise harbor innate resistance, to artesunate treatment." (PMID 33652561, 2021). "Hence it was suggested that CTHRC1, by activating EGFR signaling, promotes metastasis in ovarian cancer, which is mediated through ERK1/2, PI3K/AKT." (PMID 33859913, 2021). "In this study, we found that increased STAT3 activity after EGFR knockdown could partially explain the unsatisfactory results of anti-EGFR targeted therapy in ovarian cancer patients." (PMID 34369236, 2021). "Moreover, numerous studies have indicated that up to 60% of epithelial ovarian cancer displays EGFR overexpression." (PMID 34445495, 2021). "In summary, these findings highlight a vital role of miR-146b in ovarian cancer and might provide insights into its potential use as a strategy to improve the clinical benefit of EGFR-targeted treatment of ovarian cancer." (PMID 34369236, 2021). "However, inhibition of EGFR signalling in ovarian cancer patients resulted in a disappointing clinical benefit." (PMID 34369236, 2021).
ovarian carcinoma (continued). "Therefore, our findings suggested that the IL-6-STAT3 pathway was activated by the EGFR signalling pathway in ovarian cancer." (PMID 34369236, 2021). "However, the application of several different EGFR inhibitors for ovarian cancer treatment has shown limited benefit when these agents are used as single therapies." (PMID 34369236, 2021). "Blockade of the STAT3 pathway might be an effective strategy for increasing the therapeutic efficacy of targeting EGFR in ovarian cancer cells." (PMID 34369236, 2021). "The epidermal growth factor receptor (EGFR) is expressed in 70% of ovarian cancers." (PMID 33800113, 2021). "Human epidermal growth factor receptor 2 (HER2) and epidermal growth factor receptor (EGFR) are two examples of overexpressed antigens which have been implicated and negatively associated with prognosis in most epithelial cancers including ovarian cancer." (PMID 33920983, 2021). "About 30–70% of patients with ovarian cancer demonstrate overexpression of EGFR." (PMID 33920983, 2021). "For example, a nanoparticle consisting of VP and the Cetuximab, an epidermal growth factor receptor (EGFR)-blocking antibody, has the potential to kill ovarian cancer cells and could thus be used for the increasing treatment efficacy of CR-PDT." (PMID 34066508, 2021). "Finally, our data demonstrated that miR-146b overexpression resulted in a greater suppression of cell migration than STAT3 pathway inhibition alone.These results suggest a complex and heterogeneous role of EGFR in ovarian cancer." (PMID 34369236, 2021). "EGFR-targeted therapy drugs like Cetuximab and Trastuzumab, which are already in the use for treatment of NSCLC and metastatic CRC, lead to a better prognosis and have recently been suggested as potential treatments for ovarian cancer because of the overexpression of EGFR in ovarian cancer." (PMID 32042390, 2020). "EGFR/AKT signaling pathway involved in ovarian cancer cell differentiation via regulating TSA." (PMID 32897242, 2020). "It has also been reported that resveratrol inhibits EGFR phosphorylation in ovarian cancer cells." (PMID 32318334, 2020). "AKT1 and EGFR play major roles in tumour progression and metastasis in ovarian cancer." (PMID 31895688, 2020). "Indeed, EGFR activation increases PAF production in ovarian cancer cell lines in a PLA2-dependent mechanism." (PMID 33392068, 2020). "However, PAFR-mediated EGFR transactivation has only been demonstrated in ovarian cancer cells so far." (PMID 33392068, 2020). "Thus, in the present study we evaluated a long-term influence (“sensitization”) of anti-EGFR TKIs on ovarian cancer cells." (PMID 31546690, 2019). "Therefore, in the present study we co-incubated anti-EGFR sensitized ovarian cancer cells with NK cells and determined that CD107a expressed on NK cells during degranulation was a marker for granzyme/perforin-mediated cytotoxicity." (PMID 31546690, 2019). "However, at the same time, we also observed the reduced production of cytokines when NK cells were exposed to anti-EGFR TKI-sensitized ovarian cancer cells." (PMID 31546690, 2019). "For instance, epidermal growth factor receptor (EGFR) may be prioritized as a target for ovarian cancer." (PMID 31372215, 2019). "Interestingly, E2F3a was found to be essential in EGFR-mediated proliferation in ovarian cancer cells." (PMID 30967995, 2019). "Then, we tested anti-EGFR-sensitive as well as anti-EGFR-resistant ovarian cancer cells." (PMID 31546690, 2019).
ovarian carcinoma (continued). "In summary, anti-EGFR TKI sensitization of ovarian cancer cells led to enhanced functional resistance to anti-EGFR TKIs which could not be compensated by cetuximab sufficiently." (PMID 31546690, 2019). "Furthermore, E2F3a stimulates the proliferation of ovarian cancer cells through EGFR-driven mitogenic cell signals." (PMID 31419939, 2019). "Inversely, neither long-term treatment with TKIs nor cetuximab could overcome the intrinsic resistance of certain ovarian cancer cells to anti-EGFR agents." (PMID 31546690, 2019). "Among potential targets for the treatment of ovarian cancer, the epidermal growth factor receptor (EGFR) may be promising since EGFR is overexpressed in most ovarian cancers and is correlated to poor prognosis." (PMID 31546690, 2019). "However, clinical studies evaluating specific anti-EGFR drugs in unselected ovarian cancer patient populations have failed so far to show a relevant clinical benefit." (PMID 31546690, 2019). "In our own previous studies, we showed that the resistance of ovarian cancer cells to the anti-EGFR antibody cetuximab could be partially overcome by adding NK cells mediating antibody-dependent cellular cytotoxicity." (PMID 31546690, 2019). "EGFR is overexpressed in most ovarian cancers, which is correlated with poor prognosis." (PMID 31546690, 2019). "Hence, ANGII transactivation of the EGFR signaling pathway in the ovarian cancer cells is a ligand-dependent mechanism." (PMID 30845964, 2019). "In conclusion, based on our data on ovarian cancer, we can argue that anti-EGFR TKIs may indirectly enhance NK cytotoxicity via structural changes on ovarian cancer cells." (PMID 31546690, 2019). "Transactivation of EGFR by G protein–coupled receptors (GPCRs) is widely believed to be an important physiological process for cancer development, although the importance of GPCRs in ovarian cancer is not well understood." (PMID 30845964, 2019). "Similarly, there are also examples of increased expression of TGFα in stromal fibroblasts by secreted TNFα from cancer cells and in-turn, stimulation of EGFR signaling in ovarian cancer cells by TGFα secreted from omental fibroblasts." (PMID 31426393, 2019). "In this study, using prostate and ovarian cancer cells, by comparing the autophagic phenotypes induced by EGFR TKI and by reduction of EGFR protein, we found a unique kinase-independent pro-survival function of EGFR, which is repression of selective mitophagy by inhibiting the mTROC2/Akt axis." (PMID 29358623, 2018). "Our results are similar to the previous research that EGFR is reported to overexpressed in most ovarian cancer, and the activation of the EGFR pathway has impact on invasion and metastasis as well as cell survival through the MAPK/ERK, PI3K/AKT and Rac1 pathways." (PMID 29510732, 2018). "Recent research supports our finding that ST3GAL1 expression is increased in serous ovarian cancer and demonstrates that ST3GAL1 may regulate ovarian cancer cell migration and peritoneal dissemination via epidermal growth factor receptor (EGFR) signaling." (PMID 30375371, 2018). "The results of a meta-analysis of 15 studies involving 2471 patients with ovarian cancer for the EGFR expression found positive EGFR immunostaining in 6.2% to 72.6% (median 35%) of tumours, and in 7 studies (63.6%) EGFR expression was found to be predictive of a poorer overall survival." (PMID 29731973, 2018). "Activation of EGFR/Erk1/2 and JAK could enhance invasiveness of cisplatin-resistant ovarian cancer cells in vitro, and the inhibition of both EGFR and JAK appeared to be an efficient approach to treat human ovarian cancer." (PMID 30001383, 2018).
ovarian carcinoma (continued). "An anti-EGFR scFv appended with a SNAP tag was site-specifically coupled to an IR700 dye (DAR 1) to give a visible fluorescent conjugate with photo-immunotoxicity values in the 45–66 nM range for EGFR-expressing ovarian cancer cell lines." (PMID 31544868, 2018). "We have previously shown that lapatinib, an EGFR/ErbB2 kinase inhibitor, inhibits invasion and alters the lysosomal distribution from predominantly peripheral to predominantly perinuclear in ErbB2-positive ovarian cancer cells." (PMID 29396433, 2018). "In addition, we proved an activation of EGFR-downstream mediator ERK in all three ovarian cancer cell lines." (PMID 29662625, 2018). "Other EGFR inhibitors such as gefitinib, erlotinib, lapitinib and anti-EGFR antibodies that are used in cancer therapy need to be considered in combination with ST inhibitors and their efficacy and safety for ovarian cancer patients needs to be evaluated." (PMID 28423672, 2017). "Furthermore, LH appears to activate the PTP pathway via Ga(i) and counteracts mitogenic signal transduction induced by EGF, suggesting that the interaction of LHR and EGFR is essential for determining the fate of ovarian cancer cells." (PMID 28439256, 2017). "Limited effectiveness of therapeutic agents targeting epidermal growth factor receptor (EGFR) in clinical trials using unselected ovarian cancer patients has prompted efforts to more effectively stratify patients who might best benefit from these therapies." (PMID 28740577, 2017). "Therefore, in this study, we investigated the prognostic value of ST3GalI and its relationship with EGFR signaling in ovarian cancer using both in vitro and in vivo models including human ovarian cancer patient microarray datasets." (PMID 28423672, 2017). "Linear regression analysis of our Proseek® data had found six of these proteins to have a statistically significantly trend (p < 0.001); CA125, CXCL13, CD40L, CD69, and LAP.TGF-β1 levels were higher in ovarian cancer serum samples, while EGFR levels were lower." (PMID 29051715, 2017). "Moreover, GALNT6 modifies EGFR O-glycosylation and plays critical roles in malignant phenotypes of ovarian cancer cells." (PMID 28388560, 2017). "Co-Immunoprecipitation analysis demonstrated that EGFR and ST3GalI were physically present in the same protein complex since ST3GalI was found in the complex immunoprecipitated from ES2 ovarian cancer cell lysates with anti-EGFR antibodies and EGFR was immunoprecipitated with anti-ST3GalI antibody." (PMID 28423672, 2017). "Given the clinical predilection of Her2-amplified tumors to develop brain metastases, we explored interactions between Her2 and TrkB because TrkB heterodimerization with EGFR could increase proliferation and migration in ovarian cancer cells." (PMID 28446206, 2017). "This is the first to show the correlation between GALNT6 and EGFR activity in ovarian cancer." (PMID 28388560, 2017). "However, despite a clear implication of EGFR in cancer progression, clinical results with EGFR inhibitors were disappointing in ovarian cancer." (PMID 28446239, 2017). "Also, a recent clinical study agrees with our finding, showing that lapatinib had a minimal activity and only a small fraction of ovarian cancer overexpressed EGFR and ERBB2 (HER2)." (PMID 27558154, 2016). "Clinical trials of EGFR inhibition in ovarian cancer have been disappoint­ing to date." (PMID 27888800, 2016). "Likewise, combination treatment of a PARP inhibitor and a selective EGFR inhibitor erlotinib in ovarian cancer A2780 xenografts had an apparently enhanced antitumor effect via enhancing autophagy compared to their monotherapy." (PMID 27825125, 2016). "Therefore, the down-regulation of SPRY2 in ovarian cancer decreases its ability to inhibit EGFR-mediated cellular functions, which subsequently contributes to tumor progression." (PMID 27835572, 2016).